NF2 (NF2, moesin-ezrin-radixin like (MERLIN) tumor suppressor)
Diseases named in the same sentence as NF2 in open-access papers (continued):
Sharing a sentence is not in itself a finding about the gene and the disease.
tumor (continued). "Tumor 399, present in a patient with NF2, also showed the mutation in the peripheral blood sample." (PMID 23354516, 2013). "We therefore concluded that, at the miRNA level, a few miRNA subsets may have relevance depending on the genetic status of the tumor (the presence of NF2 mutation and/or LOH of 22q), although more research needs to be conducted on this particular aspect." (PMID 23776562, 2013). "Deletion of this putative tumor suppressor may have similarly changed a generally mild phenotype associated with complete deletion of NF2 to the severe phenotype seen in PRS-NF2." (PMID 22436304, 2012). "Mitotic recombination was the cause of LOH in 14 out of 72 total evaluable NF2 tumours." (PMID 22567403, 2012). "Moreover NF2 deficiency in humans is not accompanied by hepatic tumourigenesis, and the role of either pathway in the tumours resulting from human NF2 deficiency, as compared to NF2 inhibition of the CRL4DCAF1 ubiquitin ligase is an open question." (PMID 21102585, 2011). "Analysis of tumour tissue showed loss of the ring 22 and in addition a pathogenic NF2 mutation." (PMID 19772601, 2009). "In addition NF2 mutation analysis on the tumour tissue showed a somatic splice-site mutation on the remaining chromosome 22." (PMID 19772601, 2009). "In this study, we used our human model of early-stage PDAC combined with CRISPR screening to identify additional tumor suppressor driver mutations that may offer potential treatment options, and discovered NF2 inactivation as a potent driver of acinar-derived PDAC." (PMID 41480763, 2026). "However, among NF2‐VS patients, younger age (≤ 19 years) was associated with poorer tumor control, suggesting that age may be a critical factor in treatment decisions." (PMID 41454441, 2026). "The tumor suppressor protein merlin is encoded by NF2, and mutations may promote tumor development." (PMID 40447281, 2025). "Moreover, the specific type or locus of mutations within the NF2 gene may affect the phenotypic diversity of tumor manifestations." (PMID 41209567, 2025). "In cases of tumor reappearance, other features associated with a higher risk of recurrence, such as a high Ki-67 labeling index, incomplete surgical removal, or occurrence in the context of neurofibromatosis type 2 (NF2), were present, suggesting that the relapse was independent of brain invasion." (PMID 39202270, 2024). "Thus, the effect of NF2 loss on MEK inhibitor response may be cell- or tumor-type specific, and concurrent epigenetic mechanisms such as PRC2 loss in de-differentiated Schwann cell tumors may contribute to these responses." (PMID 38216572, 2024). "COX-induced PGI2 may play a role in the tumor microenvironment (TME) of NF2-deficient VSs." (PMID 38879686, 2024). "Moreover, our results indicate that ICAM-1 may substitute for CD44 function as a coreceptor of receptor tyrosine kinase MET, and thus may compensate for CD44 loss during other tumor-relevant processes in Nf2-deficient livers." (PMID 37174657, 2023). "Thus, NF2-associated VS are the more aggressive tumor entity." (PMID 37627117, 2023). "Merlin is a tumor suppressor, able to integrate different mechanisms and deputed to regulate signaling pathways contributing to cell proliferation, adhesion, motility, and survival; therefore, mutations in NF2 are strongly associated with SC oncotransformation." (PMID 34360009, 2021). "Interestingly, NF2 mutations are enriched in higher-grade tumours." (PMID 32070062, 2020). "Additionally, NF2 mutation was significantly associated with larger tumor volume." (PMID 31191822, 2019). "Additionally, NF2 mutation status was associated with several tumor features." (PMID 31191822, 2019). "Thus, finding a small tumor volume on preoperative imaging may be a fair indicator of non-NF2 mutational status, but larger cohorts are needed to support this finding." (PMID 31191822, 2019).
tumor (continued). "Thus, inhibiting Yes and the subsequent transcriptional activity of YAP1 had a substantial anti-tumor cell effect both in vitro and in vivo and may provide a viable therapeutic approach for patients with NF2-deficient PRCC." (PMID 29535838, 2018). "Additionally, since even NF2 disease tumours are thought to arise only after multiple mutation hits, an alternate model would be the simultaneous deletion of other tumour suppressors to lower the tumour barrier and thus elicit differential tumour formation behaviour in iso1ko and iso2ko mice." (PMID 26258444, 2015). "Therefore, in patients with deactivating NF2 mutations, one could hypothesize that an mTOR inhibitor would restore merlin's inhibition of mTOR and arrest tumor formation." (PMID 24393766, 2014). "The phenotypic distinction among patients with NF2 can have an impact on the effectiveness of tumor control following SRS." (PMID 41454441, 2026). "Fimepinostat is a promising new drug intervention for NF2-SWN patients with the potential to promote tumor regression." (PMID 41898501, 2026). "In contrast, NF2 KO in these cultures resulted in successful tumor formation (n = 6 and 4, respectively)." (PMID 41480763, 2026). "Here, we demonstrate that genetic ablation of focal adhesion kinase (Fak/Ptk2) impairs tumor formation and preserves hearing in a murine model of NF2." (PMID 41616055, 2026). "In contrast, the matched NF2‐VSs cohort had tumor control rates of 95.4%, 88.1%, and 79.9% at 1, 3, and 10 years, respectively." (PMID 41454441, 2026). "Given that NF2 is a well-established tumor suppressor gene, we focused on subsequent analyses of INSIG1 and ACSL3." (PMID 41564380, 2026). "Analysis of The Cancer Genome Atlas (TCGA) PDAC cohort revealed that lower NF2 expression correlates with a poorer prognosis, especially in patients with a classical subtype, suggesting a tumor-suppressive role for this gene." (PMID 41480763, 2026). "Our findings demonstrate the tumor-suppressive role of NF2, which is consistent with a previous study showing that NF2 overexpression in PDAC cell lines suppresses cell growth." (PMID 41480763, 2026). "NF2-SWN management primarily relies on serial annual surveillance imaging to track tumor progression and evaluate risks to adjacent critical structures, given the limited effectiveness of pharmacologic, radiation, and surgical treatments." (PMID 40842873, 2025). "NCH93 LUC2 NF2−/− cells engraft in NSG mice with ANXA3 KD showed reduced tumour growth after 29 days, as monitored by the IVIS imaging system compared to SCR controls." (PMID 40562609, 2025). "Evaluation of the therapeutic interventions in NF2 should encompass effect on tumor size, hearing, toxicity, and symptomatic response, including vestibular symptoms." (PMID 39941885, 2025). "In conclusion, our findings demonstrate that microRNA‐223‐3p significantly enhances the proliferation and tumor growth of TPC‐1 tumor cells in vivo, partly through its targeting and downregulation of NF2 protein." (PMID 39712860, 2025). "That year, the NF1 gene was localised to chromosome 17q using family linkage and the NF2 gene to 22q using tumour analysis and family linkage." (PMID 41160189, 2025). "Molecular biomarkers, including Ki-67 proliferation index, NF2 gene status, TERT promoter mutations, and H3K27me3, which are pivotal for tumor classification and prognosis have been the subject of study of recent radiomic studies." (PMID 41339597, 2025).
tumor (continued). "Among the 3 subtypes, GP1 showed particularly worse survival, while GP3 had relatively better survival, the highest proportion of tumor with low TMB, and the highest frequency of NF2 mutation." (PMID 40917497, 2025). "Our study reveals that NF2-EVs not only facilitate the transformation of monocytes into MDSC-like cells but also amplify the proliferation of tumor cells, highlighting their critical importance in the progression of NF2-associated tumors." (PMID 41149489, 2025). "In head and neck cancer, mutations or reduced expression of the NF2 gene often result in abnormal nuclear translocation of YAP/TAZ, thereby activating oncogenic gene expression and correlating with increased tumor invasiveness and poor patient prognosis." (PMID 40486910, 2025). "Given the oncogenic role of NF2 loss in PM, the prevalence of NF2 alterations in Cluster 1, and the poor prognosis associated with this metabolic subtype, we further investigated the role of NF2 in tumor metabolism." (PMID 40707702, 2025). "Mosaic NF2-SWN frequently demonstrates asymmetry with tumours predominantly on one side or one body segment or can be indistinguishable from non-mosaic patients with bilateral disease." (PMID 41160189, 2025). "NF2-associated VSs tend to be more invasive and to have a higher degree of dividing cells than non-NF2 tumours." (PMID 40843672, 2025). "This establishes a synthetic lethal relationship: NF2-mutant tumor cells exhibit dependency on FAK signaling for survival." (PMID 41487565, 2025). "NF2 tumours exhibited more immune cells than AKT1 E17K or KLF4 K409Q, and AKT1 E17K showed slightly higher immune cell counts than KLF4 K409Q." (PMID 40420192, 2025). "The NF2 mRNA expression was analysed in a series of VSs using Northern blotting, including samples from 13 tumours related to NF2." (PMID 40843672, 2025). "NF2 mutations occur in all grades and AKT1 E17K and KLF4 K409Q often co-occur with TRAF7 mutations predominantly in grade 1 tumours." (PMID 40420192, 2025). "Using further work on testing of tumours, the current estimate for mosaicism in a de novo NF2-SWN case is close to 60%." (PMID 41160189, 2025). "In all patients with NF2 (100%), two or more hits were detected in the tumor DNA, whereas patients with uVS had a slightly lower detection rate (89–98%)." (PMID 39941762, 2025). "In vivo, NF2 overexpression abrogated the iEV-150-induced reduction in tumor volume and weight in the mice." (PMID 40860143, 2025). "There were no other significant associations between merlin immunoreactivity and NF2 status, WHO grade, tumor subtype, tumor location or gender." (PMID 40447281, 2025). "These two samples were the only ones among the eight NF2-related tumours that exhibited aberrant NF2 promoter hypermethylation, indicating that this epigenetic change is rare in this patient subgroup." (PMID 40843672, 2025). "Further data reporting with increasing granularity is needed to elucidate a potential association between NF2, NF1 and seizure activity or tumor grade in PM." (PMID 40637916, 2025). "A two-year-old patient with a history of neurofibromatosis type 1 (NF1), NF1 microdeletion and variants of uncertain significance in the CASR, NF2, and POLD1 genes, presented with intestinal subocclusion caused by a 15 cm heterogeneous pelvic tumor." (PMID 40630346, 2025). "The NMR HA appears to shield or block excessive CD44 binding and support normal cellular signalling through Src-MAPK, and unique Merlin/NF2-pALTINK4a/b novel signalling pathways suppressing tumour growth and invasion and instilling contact inhibition of cells." (PMID 39852021, 2025). "This trial was a phase II, prospective, multicenter trial that enrolled patients aged 12 years and older with NF2-SWN and the progression of an NF2-SWN-related tumor." (PMID 40862786, 2025). "It is necessary for two somatic mutations to occur in a single cell to escape the normal function of the NF2 gene which acts as a tumor suppressor." (PMID 41300330, 2025).
tumor (continued). "Research has indicated that the E-cadherin-neurofibromin 2 (NF2)-Hippo signaling pathway exerts both tumor-suppressive and ferroptosis-suppressive effects." (PMID 40709182, 2025). "As such, our spatial analyses highlight a clinical rationale for selected combinatorial treatment for VS tumours in NF2 SWN." (PMID 40140675, 2025). "RNA-seq confirmed these observations, showing a higher proportion of immune cells in NF2 tumours, particularly macrophages and M2 macrophages." (PMID 40420192, 2025). "These tumor suppressor genes found on chromosome 22, near the NF2 region, include SMARCB1 and LZTR1." (PMID 40337438, 2025). "In June 2023, a tumor biopsy of the lower abdomen was performed, and the pathological diagnosis confirmed NF2." (PMID 40852360, 2025). "Although research in this area is nascent, one study in neurofibromatosis type 2 (NF2) – a tumor syndrome – indicated malonylation’s involvement in lipid metabolic changes that support tumor growth." (PMID 41107644, 2025). "The most significant is the small sample size, particularly the limited number of familial cases with matched blood-tumor pairs (n=3), which is inherent to research on rare diseases like NF2-SWN." (PMID 41209567, 2025). "Extending beyond promoter silencing, genome-wide methylation profiling has revealed that NF2-associated VSs also exhibit extensive DNA hypomethylation, particularly in oncogenes and regulatory miRNAs, suggesting broader epigenetic dysregulation that may promote tumour development." (PMID 40843672, 2025). "As a tumour suppressor gene, the NF2 gene requires biallelic inactivation to initiate tumour development." (PMID 41284083, 2025). "Prussian blue staining revealed that iEV-150-driven iron accumulation in tumors was reduced by NF2 overexpression, and TUNEL staining confirmed that NF2 overexpression attenuated iEV-150-induced tumor cell death." (PMID 40860143, 2025). "To gain deeper insights into the biological properties and activities of NF2-EVs within the tumor microenvironment, we conducted a comprehensive proteomic analysis of these tumor-derived extracellular vesicles using mass spectrometry." (PMID 41149489, 2025). "Further analysis revealed that NF2 tumours had the highest proportions of M2-like TAMs and microglia within their respective populations." (PMID 40420192, 2025). "These are frequently observed alongside NF2 alterations, reflecting a stepwise accumulation of genetic changes driving tumor progression." (PMID 40951339, 2025). "The current lack of alternative treatments for NF2 SWN-related VS is a consequence of our limited understanding of the biology of NF2 SWN-related VS tumours." (PMID 40140675, 2025). "Consistent with the tumor-suppressive role of NF2, genetic knockout of NF2 dramatically increased the tumor burden in both subcutaneous and orthotopically transplanted PM mouse models." (PMID 40707702, 2025). "In line with that, our CRISPR-mediated knockout experiments confirmed that NF2 depletion enhanced tumor aggressiveness in vitro and in vivo (Fig. EV1A–G)." (PMID 40707702, 2025). "VSs, especially in patients with NF2, pose a significant challenge due to tumor growth and its impact on hearing and nerve function." (PMID 39685944, 2024). "Growing evidence also highlights the link between NF2 and cancer metabolism reprogramming, as well as tumor immunity." (PMID 38879686, 2024). "The changes in the NF2/MOB1-YAP signaling pathway in tumor cells after BUB1 knockdown and GEM treatment were examined using Western blot." (PMID 38672622, 2024). "Upon phosphorylation, NF2 assumes its “open” conformation, inactivating its tumor suppressor activity." (PMID 39796693, 2024). "By prioritizing studies with mixed-age cohorts or adult populations, this review aims to maintain a more consistent analytical basis for evaluating bevacizumab’s effects on tumor volume, hearing preservation, and adverse events in NF2-related VS." (PMID 39685944, 2024).
tumor (continued). "Among the identified genes, NF2 (Neurofibromatosis type 2) has been well-documented as an important tumor suppressor gene in biliary carcinogenesis." (PMID 38641672, 2024). "Perhaps the most extensively researched mechanistic pathway relevant to the tumor suppressor activity of the NF2 gene in sporadic meningiomas, as well as other cancers, is the Hippo signaling pathway." (PMID 39796693, 2024). "Another study with human sarcomatoid nccRCC tumor specimens reiterated the involvement of the Hippo signaling pathway in NF2-mutant RCC tumors." (PMID 39796693, 2024). "Treatment with bevacizumab, a humanized monoclonal antibody that specifically neutralizes VEGF-A, has been documented to lead to hearing improvement or tumor shrinkage in 30–60% of NF2 patients and is approved for NF2 treatment in the United Kingdom." (PMID 38893082, 2024). "Our studies demonstrated that these methods, paired with hearing tests, enable a comprehensive evaluation of tumor-induced neurological deficits and facilitate the assessment of the effectiveness of novel therapeutics to improve NF2 treatments." (PMID 38893082, 2024). "The primary objective of this study is to conduct a systematic literature review, following the PRISMA guidelines, to evaluate the efficacy of bevacizumab in controlling tumor volume and preserving hearing function in patients with VS and NF2." (PMID 39685944, 2024). "In particular, the expression of YAP reduced as cell density increased in human CRC samples, which was reliant on the expression of the tumor-suppressor NF2." (PMID 39431199, 2024). "Patients with NF2 generally receive screening for VS at diagnosis, leading to earlier diagnosis, smaller tumor sizes, and a more aggressive course of treatment." (PMID 38892775, 2024). "The panel NGS of the primary tumor revealed pathogenic mutations in VHL, BAP1 and NF2 and likely pathogenic mutations in KDM6A, as well as ABL." (PMID 38611655, 2024). "Changes in signal intensity values within the tumor area in the SWI emerged as significant indicators of both S100 protein expression and NF-2 mutations." (PMID 38611661, 2024). "Loss of function or genetic mutations in Hippo kinases like NF2 and LATS1/2 leads to the activation of YAP, fostering positive interactions with other pathways and driving tumor progression." (PMID 38396367, 2024). "Cell–cell contact inhibition is another way in which NF2 regulates cell activity as a tumor suppressor." (PMID 39796693, 2024). "The results demonstrated that changes in signal intensity values within the tumor area in SWI are significant indicators for both S100 protein expression and NF-2 mutations." (PMID 38611661, 2024). "Another study looked at the phosphorylation of NF2 at Ser518 by PAKs, which inactivates the tumor suppressive effects of NF2." (PMID 39796693, 2024). "Efforts to understand the molecular pathways driving tumor development in NF2 have led to the reconsideration of existing cancer drugs for potential use in NF2 patients." (PMID 39618887, 2024). "Examples include inactivation of the E-cadherin–neurofibromin 2 (NF2)-Hippo signaling axis and loss of the Von Hippel-Lindau (VHL) tumor suppressor." (PMID 38562143, 2024). "These methods, paired with hearing tests, enable a comprehensive evaluation of tumor-induced neurological deficits and facilitate the assessment of the effectiveness of novel therapeutics to improve NF2 treatments." (PMID 38893082, 2024). "In this way, NF2 acts as an essential tumor suppressor, inhibiting the development of several cancer types." (PMID 39796693, 2024). "With YAP1 knockdown and NF2 reconstitution, they found that tumor growth and proliferation was inhibited." (PMID 39796693, 2024).